CDKN2A (cyclin dependent kinase inhibitor 2A)
Diseases named in the same sentence as CDKN2A in open-access papers (continued):
Sharing a sentence is not in itself a finding about the gene and the disease.
thyroid cancer (18 papers, 2006 to 2025). "The activity of CDKN2A is often diminished or entirely lost in thyroid cancer due to mutations, homozygous deletions, and promoter hypermethylation." (PMID 40363930, 2025). "The increased expression of CDKN2A gene product is associated with thyroid cancer progression." (PMID 37221474, 2023). "Nervous system and thyroid cancers also showed independent support for being true associations, both may also manifest CDKN2A mutations or deletions." (PMID 28198461, 2017). "A genetic analysis of 779 advanced differentiated and anaplastic thyroid cancers revealed CDKN2A inactivation in approximately 7% of advanced differentiated thyroid cancers." (PMID 40363930, 2025). "For example, CDKN2A and NRAS alterations, which were mutated in 8.1% and 11.3% of thyroid cancers respectively in Black patients, were more common in Black than White patients." (PMID 38297963, 2024). "A pan-cancer survival analysis revealed that CDKN2A-ALT patients had a shorter OS than CDKN2A-WT patients in 23 cancer types, including thymic epithelial tumor, thyroid cancer, renal non clear cell carcinoma, salivary gland cancer, gastrointestinal stromal tumor, adrenocortical carcinoma and so on." (PMID 38822443, 2024). "Promoter methylation status of genes with reported associations in thyroid cancer (CASP8, CDKN2A, DAPK1, ESR1, NIS, RASSF1 and TIMP3) were examined in a cohort of follicular thyroid cancers comprising of 26 Hurthle and 27 Classic subtypes utilizing quantitative methylation-specific PCR." (PMID 27158284, 2015). "Besides, the bioinformatic analysis found that genes related to the cell cycle (i.e., CDKN2A, CDKN2B, CCNE1, etc.)were mutated or abnormally expressed in ATC, which might provide another thought in advanced thyroid cancers." (PMID 34900720, 2021). "This increased thyroid cancer risk remained higher until 60 months after the index CMM, which could suggest the involvement of cancer-promoting genetic abnormalities (i.e., BRAFv600e, CDKN2A) which could potentially be involved in the pathogenesis of both malignancies." (PMID 37397750, 2023). "Compared with normal thyroid tissue, 7 CRGs were more highly expressed in thyroid cancer, namely BUB1 (P<0.001), RPL3 (P<0.001), TTK (P<0.001), GINS2 (P<0.001), SLC26A6 (P<0.001), CDKN2A (P<0.001) and ZNHIT2 (P<0.001)." (PMID 37745716, 2023). "In conclusion, we developed a novel seven-mRNA (CDKN2A, FGF7, CTSB, HAP1, DAPK2, DNAJB1, ITPR1) risk model and nomogram that could help assess the prognosis of patients and guide clinical decision-making and individualized therapy for differentiated thyroid cancer." (PMID 35459137, 2022). "Another study found that while CDKN2A alterations were present in some advanced differentiated thyroid cancers, they were absent in minimally invasive follicular and papillary thyroid cancer specimens." (PMID 40363930, 2025). "Though three genes, i.e., RET, CDKN2A, and JAK2, are not enriched in a cancer related pathway with other detected genes, they are believed to have a close relationship with thyroid carcinoma." (PMID 37221474, 2023).
Alzheimer disease (17 papers, 2012 to 2025). A progressive, neurodegenerative disease characterized by loss of function and death of nerve cells in several areas of the brain leading to loss of cognitive function such as memory and language. "Importantly, CDKN2A has already been implicated as a regulator and biomarker of human Alzheimer's disease (AD), however, its exact link to disease occurrence and progression is still unclear." (PMID 33981746, 2021). "It is important to note that CDKN2A and IFNA17 were enriched in Alzheimer’s disease." (PMID 36506471, 2022).
penile cancer (17 papers, 2008 to 2025). A primary or metastatic malignant neoplasm that affects the penis.
pleomorphic xanthoastrocytoma (17 papers, 2016 to 2026). A WHO grade ll astrocytic tumor with a relatively favorable prognosis. "BRAF V600E-mutated pLGGs with the presence of the CDKN2A (Cyclin-Dependent Kinase Inhibitor 2A) deletion, more commonly described in pleomorphic xanthoastrocytoma, have a highly increased risk to transform to HGG in one or two decades." (PMID 34572171, 2021). "Reports suggest that CDKN2A loss ranges in frequency from 6-20% in pLGG, with significant enrichment in pleomorphic xanthoastrocytoma." (PMID 32164789, 2020). "Both the pleomorphic xanthoastrocytoma and diffuse astrocytoma were found to have homozygous deletion of CDKN2A/B due to somatic loss of the other copy of chromosome 9p containing the remaining intact alleles." (PMID 28699883, 2017). "Notably, co-occurrence of BRAF V600E mutation and CDKN2A co-deletion moreover showed a significant enrichment in pleomorphic xanthoastrocytoma, a PLGG type known for an increased tendency of malignant transformation to sHGG." (PMID 39056798, 2024). "Notably, co-occurrence of BRAF V600E mutation and CDKN2A co-deletion moreover showed a significant enrichment in pleomorphic xanthoastrocytoma, a PLGG type known for an increased tendency towards malignant transformation." (PMID 39056798, 2024). "CDKN2A deletions were detected in exons 1 and 2 in 1 (pleomorphic xanthoastrocytoma) sample of 9 samples analyzed." (PMID 35574540, 2022). "The increased likelihood of malignant behavior in pleomorphic xanthoastrocytoma and in BRAF p.V600E mutated tumors with CDKN2A deletion has led to a debate regarding the prognostic significance of BRAF p.V600E alone." (PMID 32164789, 2020). "pLGG in vitro cell line models derived from human primary tumors range from PA with a BRAF-fusion or -V600E mutation only (DKFZ-BT66, -BT308, -BT314, and -BT317) or NF1 loss (JHH-NF1-PA1), to pleomorphic xanthoastrocytoma (PXA) with BRAFV600E mutation and CDKN2A/B deletion (BT40)." (PMID 38789691, 2024). "The methylation-based classification suggested anaplastic pleomorphic xanthoastrocytoma (-like) (PXA, score 0.99, Classifier 12.5), no MGMT promotor methylation, and the derived CNV profile indicated a homozygous deletion (HD) of CDKN2A/B." (PMID 41331048, 2025).
chondrosarcoma (16 papers, 2008 to 2026). A malignant cartilaginous matrix-producing mesenchymal neoplasm arising from the bone and soft tissue. "Our findings indicate that if a tumour shows p16/CDKN2A copy number variation (gain or loss), it should be managed as a high grade chondrosarcoma." (PMID 25432631, 2015). "In similarity with hyperhaploid-hypodiploid ALL which commonly display loss of CDKN2A, all the present hyperhaploid-hypodiploid chondrosarcomas showed deletion of this gene." (PMID 21949816, 2011). "The 62 % of the dedifferentiated chondrosarcomas (13/21) also revealed p16/CDKN2A loss." (PMID 25432631, 2015). "Our results suggest that deletions in cell cycle regulators CDKN2A and RB1 are associated with increased radioresistance in chondrosarcoma explant tissue." (PMID 31160965, 2019). "Deletions in CDKN2A/B genes were noted in undifferentiated pleomorphic sarcoma and chondrosarcoma." (PMID 41562936, 2026). "We report here three new chondrosarcoma cell lines lacking p16 expression based on a homozygous deletion of the CDKN2A locus as shown by aCGH analysis, and confirmed loss of p16 expression using immunohistochemistry." (PMID 22928481, 2012). "Previous reports have demonstrated lack of CDKN2A specifically in high-grade chondrosarcomas and suggested that this deficiency affects cell viability and proliferation." (PMID 21949816, 2011). "In addition, we identified alterations in CDKN2A/RB1 as predictors of decreased double strand break formation after radiotherapy in chondrosarcoma tissue, and although further research is necessary in a larger group, this suggests that these patients might benefit less from radiation therapy." (PMID 31160965, 2019). "Polysomy of p16/CDKN2A was detected in 2/30 GII, 1/6 GIII and 6/21 dedifferentiated chondrosarcomas." (PMID 25432631, 2015). "This is supported by our findings that in 60 low grade central conventional tumours (enchondroma/low grade chondrosarcoma), obtained from patients with a single tumour sample, none had p16/CDKN2A copy number variation." (PMID 25432631, 2015). "Specifically, p16/CDKN2A has been found to occur in high grade chondrosarcomas but rarely in chondrosarcoma grade (G) I and not in enchondromas." (PMID 25432631, 2015). "Frequent loss of chromosome arm 9p has previously been described in chordomas, and particularly, the region covering the CDKN2A (p16 and p14) and CDKN2B (p15) loci in chromosomal band 9p21 has been shown to be deleted in many tumour types, also in chondrosarcoma." (PMID 18071362, 2008). "Although we see a clear difference in the amount of foci in tumors with and without deletions in CDKN2A or RB1, this study is based on a small heterogenous group of chondrosarcomas and measurements are taken after 2 or 24 h." (PMID 31160965, 2019).
diffuse astrocytoma (16 papers, 2017 to 2025). A low-grade (WHO grade II) astrocytic neoplasm. "A critical prognostic factor in IDH-mutant diffuse astrocytomas is the presence of CDKN2A/B deletions, which are strongly associated with worse survival outcomes." (PMID 41346390, 2025). "However, since 2022, the new WHO classification has added more genetic mutations that classify diffuse astrocytoma as grade IV gliomas (homozygous CDKN2A/B deletion, TERT promoter mutation, EGFR gene amplification, and chromosome 7 gain/chromosome 10 loss)." (PMID 37534252, 2023). "In the diffuse astrocytoma, we show that the germline CDKN2A/B deletion was accompanied by somatic loss of the remaining CDKN2A/B alleles as well as an activating hotspot mutation in PTPN11 and inactivating frameshift mutations in the ATRX and NF1 tumor suppressor genes." (PMID 28699883, 2017). "We did not detect differences in histopathological features within the tumor but, the loss of CDKN2A/B in certain regions of the tumor could likely explain the rapid progression of the patient with a clinical diagnosis of diffuse astrocytoma IDH-mutant, WHO (2016) grade II." (PMID 35701666, 2022). "IDH-mutant diffuse astrocytomas are graded 2–4 within their type; in addition, in the case that an IDH-mutant diffuse astrocytoma exhibits CDKN2A/B homozygous deletion, it is classified as a CNS WHO grade 4 tumor." (PMID 40362343, 2025). "In recent years, MTAP was reported as a useful immunohistochemical surrogate marker for CDKN2A-HD in adult-type infiltrating diffuse astrocytoma (sensitivity: 88.2%, specificity: 98.3%)." (PMID 39117984, 2024). "Many studies have found that homozygous deletion of cyclin-dependent kinase inhibitor 2A/B (CDKN2A/B) in patients with IDH-mutant diffuse astrocytomas is a sign of poor prognosis." (PMID 37190513, 2023). "Several studies evidenced the role of CDKN2A/B homozygous deletion as an independent poor prognostic factor in IDH-mut diffuse astrocytomas." (PMID 35756624, 2022). "Attempts to molecularly define the aggressive type of diffuse astrocytomas have suggested several genetic markers such as RB1 pathway alterations (e.g., CDKN2A/B homozygous deletion or CDK4 amplification), PIK3R1 mutation, PDGFRA amplification, or G-CIMP low type in the methylation cluster." (PMID 33228806, 2020).
dysplastic nevi (16 papers, 2009 to 2025). "Specifically, the phototype of BRCA mutation carriers is fairly normal, in contrast to MCR1R or CDKN2A patients, which contrariwise, are usually known to have red hair or multiple dysplastic nevi, respectively." (PMID 35573021, 2022). "Furthermore, some MC1R variants can increase the penetrance of a CDKN2A mutation when occurring together, in a complex interplay between CDKN2A mutations and individual phenotypes (dysplastic nevi and poor tanning ability)." (PMID 34356093, 2021). "In particular, the phototype of LS carriers is normal, unlike MCR1R or CDKN2A patients, who tend to have red hair or multiple dysplastic nevi, respectively." (PMID 36612110, 2022).
endometriosis (16 papers, 2010 to 2025). The growth of functional endometrial tissue in anatomic sites outside the uterine body. "The evidence from the literature suggests that silencing of tumor suppressor genes such as CDKN2A by CDKN2BAS might have an important role in the development of endometriosis." (PMID 22924156, 2012). "Moreover, hypermethylation of the CDKN2A promoter region has been observed in endometriosis, and loss of heterozygosity on the CDKN2A locus has been found in endometriosis, suggesting that CDKN2A might play a role in the regulation of endometrial cell growth." (PMID 22924156, 2012). "As expected, the expression of CDKN2A was upregulated, whereas the expression of GLS and LIPT1 was downregulated in UCEC cells versus normal human endometriosis cells." (PMID 35937995, 2022).
malignant glioma (16 papers, 2003 to 2024). A grade III or grade IV glioma arising from the central nervous system. "Studies on malignant glioma have shown that deletion mutations of CDKN2A can be seen in 40.3% of cases, of which homozygous deletion accounts for 74%, and homozygous deletion is more common in patients with primary malignant glioma." (PMID 35004697, 2021). "Oncogenic BRAF mutation and CDKN2A inactivation characterize a subset of pediatric malignant gliomas." (PMID 29152094, 2017). "The CDKN2A/cyclin-dependent kinase 4, 6/Retinoblastoma protein (Rb) pathway is thought to play a crucial role in malignant gliomas pathogenesis." (PMID 21843312, 2011). "Our study suggests that CDKN2A as a malignant gliomas suppressor gene, appears to be useful for predicting behaviour of high-grade malignant gliomas." (PMID 21843312, 2011). "Overexpression of CDKN2A suppresses colony-forming ability and growth rate of human malignant glioma cells." (PMID 21843312, 2011). "We have investigated the expression of CDKN2A for potential correlations with malignant gliomas grade and potential role of CDKN2A on malignant gliomas pathogenesis." (PMID 21843312, 2011). "CDKN2A-Cyclin-Rb pathway plays a key role on malignant gliomas formation and that therapeutic targeting of this pathway may be useful in malignant gliomas treatment." (PMID 21843312, 2011).
multiple myeloma (16 papers, 2004 to 2024). "The one gene in common with our studies is the Cdkn2a locus; it is a tumor susceptibility gene in both mouse plasma cell tumors by genetic linkage studies and in genome-wide association studies (GWAS) in human multiple myeloma." (PMID 32923678, 2020). "This is the second case report of germline mutation of CDKN2A being associated with myeloma." (PMID 29110637, 2017). "In multiple myeloma (MM), a cancer affecting plasma cells, several tumor suppressor genes (e.g., CDKN2A, CDKN2B, SOCS1, and SHP1) are hypermethylated in the CpG islands of their promoters, leading to gene translation inhibition." (PMID 38248418, 2024). "Another integrative bioinformatics analysis revealed that CDKN2A shows a significant correlation with immune signatures in multiple myeloma, including CD4+ regulatory T cells, T cell exhaustion, and neutrophils." (PMID 35937995, 2022). "Moreover, methylation of BM742401 correlated with shorter OS in newly diagnosed myeloma, similar to CDKN2A and DAPK1 methylation, suggesting an adverse impact of BM742401 methylation for OS." (PMID 32855620, 2020). "The methylation loss of CDKN2A and CDKN2B is demonstrated in myeloma patients." (PMID 32633782, 2020). "Moreover, methylation of RNF130/miR-340 correlated with shorter OS in newly diagnosed myeloma, similar to CDKN2A and DAPK1 methylation." (PMID 31064412, 2019). "However, after treatment with the DNA demethylating agent decitabine at 1 μM for 3 days, leading to mRNA reactivation in KMS-12-PE myeloma cells, similar DC-PCR results were obtained as in cells expressing CDKN2A (Normal Human Dermal Fibroblasts, NHDF) or PU.1 (RPMI 8226 myeloma cells) at baseline." (PMID 22984542, 2012).
renal cell carcinoma (16 papers, 2015 to 2025). "Based on these observations, up-regulation of HMGA2 and CTHRC1, together with loss of CDKN2A, may serve as prognosis markers in renal cell carcinoma." (PMID 27144525, 2016). "Research has indicated that the silencing of MYCN can promote cell migration, while the presence of MYCN and CDKN2A correlates with tumor stage, metastasis, and overall survival in renal cell carcinoma." (PMID 40177240, 2025). "A comprehensive cytogenetic analysis using microsatellite analysis and FISH of the CDKN2A region on chromosome 9p improves the predictive accuracy of known prognostic factors in clinically localised renal cell carcinoma undergoing surgical resection." (PMID 27682877, 2016). "In addition to this, in NONO-TFE3 fused renal cell carcinoma, circMET recruits YTHDF2 by directly binding CDKN2A mRNA, which significantly impairs CDKN2A expression and leads to CDKN2A mRNA attenuation." (PMID 38125749, 2023).